USH2A (usherin)
Diseases named in the same sentence as USH2A in open-access papers (continued):
Sharing a sentence is not in itself a finding about the gene and the disease.
Dysarthria (1 paper, 2020). Dysarthric speech is a general description referring to a neurological speech disorder characterized by poor articulation. "Given the reported comorbidity between auditory processing and language impairments and the presence of dysarthria in the discovery family, we investigated whether Ush2a knockout in mice altered the properties of their ultrasonic vocalizations." (PMID 32313182, 2020).
enteropathy (1 paper, 2024). "However, to the best of current knowledge, USH2A mutations are not suggested to induce enteropathy." (PMID 38674450, 2024).
glycogen storage disease type III (1 paper, 2022). "Finally, a recent report described a case of paternal UPD resulting in homozygous mutations in both USH2A and AGL (glycogen storage disease type III) genes in a 4-year-old girl with congenital deafness, learning difficulties, and enlarged liver." (PMID 36051698, 2022).
gynecological cancer (1 paper, 2020). "Furthermore, TTN, MUC16, CSDM3, RYR2, USH2A, and SYNE1 were frequently mutated in gynecological cancers but not in the MSK-IMPACT samples, suggesting that they play specific roles in the development of gynecological malignancies." (PMID 32626534, 2020).
language disorder (1 paper, 2020). A category of disorders characterized by an impairment in the development of an individual's language capabilities, which is in contrast to his/her non-verbal intellect. "We show that USH2A variants exert direct effects upon low-frequency hearing and indirectly affect the risk of language disorder through the modulation of subsequent auditory perception and language development." (PMID 32313182, 2020). "Given the inheritance pattern and complete cosegregation, in the absence of a second pathogenic variant, we hypothesized that the observed heterozygous loss of USH2A could account for the observed language disorder in this family." (PMID 32313182, 2020).
macular holes (1 paper, 2025). A hole in the macula of the retina. "When comparing the prevalence of specific genes and comorbidities, we found the following associations in AR RP: CRB1 was statistically associated with ERM (p = 0.003), EYS with cataract (p = 0.001), PROM1 with CNV (p = 0.0026), and USH2A with macular hole (p = 0.01)." (PMID 40725401, 2025).
metastatic tumors (1 paper, 2021). "In the recurrent/metastatic tumors, patients with neoantigens in TTN, PIK3CA, and USH2A increased CD3+ CD8+ infiltration approximately 3-fold compared to patients without neoantigens in these genes." (PMID 33796222, 2021). "There were three genes (PIK3CA, USH2A, and TTN) containing neoantigens in the recurrent/metastatic tumors." (PMID 33796222, 2021).
monocytic leukemia (1 paper, 2023). "PTPN11mut was more common in myelomonocytic and monocytic leukemia, and was more likely to co‐mutate with KRAS, KMT2C, NRAS, U2AF1, NOTCH1, IKZF1, and USH2A mutations than PTPN11wt." (PMID 37937729, 2023).
Mucopolysaccharidosis type IIIC (1 paper, 2019). "In that report, USH2A gene defects were identified in 14.3% of solved cases, whereas mutations in the HGSNAT gene (typically responsible for Mucopolysaccharidosis type IIIC) were a relatively common cause of pericentral RP." (PMID 31877679, 2019).
optic nerve colobomas (1 paper, 2025). "Despite the rarity of these variants, given that there have never been reported optic nerve colobomas associated with USH2A variants, it is felt this concurrence represents sporadic coincidence rather than genetic association." (PMID 40225234, 2025).
Pearson syndrome (1 paper, 2024). Pearson syndrome is characterized by refractory sideroblastic anemia, vacuolization of bone marrow precursors and exocrine pancreatic dysfunction. "Remarkably, half of them (n = 4/8) were genotypically attributed to syndromic IRDs (syndromic: COH1, USH2A, RNU4ATAC; Pearson syndrome; isolated: RPGR, RP2, CACNA1F)." (PMID 39596324, 2024).
retinal ciliopathies (1 paper, 2024). "This review will discuss the state of hiPSC-derived retinal organoid technology for accurately modelling prominent retinal ciliopathies related to genes, including RPGR, CEP290, MYO7A, and USH2A." (PMID 38474133, 2024).
syndromic retinitis pigmentosa (1 paper, 2023). A retinitis pigmentosa that is part of a larger syndrome. "Loss-of-function mutations in USH2A are among the most common causes of syndromic and non-syndromic retinitis pigmentosa (RP)." (PMID 37313440, 2023).
thyroid autoimmune disease (1 paper, 2021). "The MUC4 mutation revealed no pathway with an FDR q-value < 0.05, whereas the USH2A mutation featured the following significantly upregulated pathways: antigen processing and presentation pathways, thyroid autoimmune disease pathways, and NK cell-mediated cytotoxic pathways." (PMID 34795697, 2021).
triple-negative breast carcinoma (1 paper, 2018). An invasive breast carcinoma which is negative for expression of estrogen receptor (ER), progesterone receptor (PR), and human epidermal growth factor receptor 2 (HER2). "Gene USH2A is another genes in BRCA results of our model, and USH2A mutations have been identified highlighting the molecular diversity observed in triple-negative breast cancers by a recent research." (PMID 29871594, 2018).
Waardenburg syndrome type 2 (1 paper, 2018). Waardenburg syndrome type 2 (WS2) is an autosomal dominant subtype of Waardenburg syndrome (WS), characterized by varying degrees of deafness and pigmentation anomalies of eyes, hair and skin, but without dystopia canthorum. "Contrary to the small range of USH2A pathogenic variants, MITF pathogenic variants causing Waardenburg syndrome type 2 are diverse and usually private, with only a small number of exceptions." (PMID 29293505, 2018).
cancer (14 papers, 2014 to 2025). A tumor composed of atypical neoplastic, often pleomorphic cells that invade other tissues. "The differential genes screened by USH2A mutation allowed the construction of a risk model for predicting the survival and prognosis of cancer patients, in addition to providing new ideas for COAD immunotherapy." (PMID 34795697, 2021). "Mutations of APOB, USH2A, and KMT2D were reported to be associated with poor prognosis in several cancer types, and could be considered targets for combination therapy." (PMID 38922489, 2024). "Interestingly, many novel cancer-associated genes identified by the excess of missense mutations are large genes with repetitive functional domains: LRP1B, CSMD3, FLG, USH2A and others." (PMID 30453881, 2018). "We also found that some of the identified genes, including TTN, MUC16, CSDM3, RYR2, USH2A, and SYNE1, are only altered in gynecological malignancies and not in other cancer types, highlighting their specific role in driving gynecological malignancies." (PMID 32626534, 2020). "Thus, in sum based on previous study, role of CSDM3, USH2A and SYNE1 is still not known in any cancer." (PMID 32626534, 2020).
tumor (12 papers, 2015 to 2025). "The most frequently mutated genes in the tumor fragments of women were USH2A, ATM, and IGF2R; in female dogs, they were USH2A, BRCA2, and RRM2." (PMID 34680380, 2021). "On the basis of two DEGs associated with the USH2A mutation, we constructed a model with a predictive effect on the prognosis of tumor survival." (PMID 34795697, 2021). "The most frequent top mutated genes in tumor fragments of women were USH2A, ATM, IGF2R, MKI67, and MAP3K1 (median variants per sample = 20; missense, nonsense, and splice site mutations)." (PMID 34680380, 2021). "The USH2A gene was one of the most frequently mutated genes observed in tumor fragments from women and dogs, as well as in the plasma of women." (PMID 34680380, 2021). "In order to further study the differential expression of tumor tissue genes after USH2A mutation, we divided TCGA COAD samples into a USH2A mutant group and a wild-type group, and we used the edgeR package to analyze the differential expression of genes." (PMID 34795697, 2021). "In this study, the survival prognosis of patients with USH2A mutations was poor; however, in the USH2A mutant tumor samples, there was an enrichment of activated NK cells, TFH cells, and γδ T cells, indicating a change in the recognition of immune surveillance, as well as an antitumor effect." (PMID 34795697, 2021). "We used TCGA dataset to analyze the tumor response to immunotherapy after USH2A mutation." (PMID 34795697, 2021). "USH2A is frequently mutated in tongue squamous cancer, and AHNAK is associated with tumor metastasis." (PMID 35993362, 2022). "The results of tumor-infiltrating immune cell analysis showed an enrichment of activated NK cells, TFH cells, and γδT cells in the USH2A mutation samples, which is consistent with the results of previous studies." (PMID 34795697, 2021). "The calculation results of KM analysis showed that the USH2A mutation and MUC4 mutation were related to tumor survival and prognosis." (PMID 34795697, 2021). "We also observed that the USH2A mutation was associated with an increased tumor mutation burden (TMB) and tumor neoantigen burden (TNB) in our cohort, indicating that mutation in USH2A might be associated with an altered immune environment." (PMID 35804832, 2022). "In tumor fragments, the BRCA2 and USH2A genes showed many variants in both species." (PMID 34680380, 2021).
genetic disease (5 papers, 2016 to 2025). "In recent studies, similar approaches were developed to activate the genes associated with various inherited diseases, including CRB1 (RP) and USH2A, in human skin fibroblasts." (PMID 41056201, 2025). "The USH2A knockout (USH2AKO) rabbit model has been utilized as an important tool for studying the pathogenesis and progression of USH2A syndrome, a genetic disorder associated with moderate to severe SNHL and RP." (PMID 38086867, 2023).
retinopathy (5 papers, 2015 to 2024). "USH2A, which encoded a protein called usherin, was reported to be mainly involved in retinopathy and hearing loss." (PMID 38384303, 2024). "Our study suggests that more severe loss-of-function mutations in USH2A lead to syndromic retinopathy." (PMID 26338283, 2015). "We observed significantly reduced levels of usherin p.(Cys771Phe) at the zebrafish photoreceptor periciliary membrane and increased levels of aberrantly localized rhodopsin, which was previously shown to be a hallmark of ush2a-associated retinopathy in a zebrafish knock-out model." (PMID 35672333, 2022). "ADGRV1 and USH2A retinopathy were indistinguishable in all major functional and structural characteristics, suggesting that the loss of function of the corresponding proteins produces similar effects in the retina." (PMID 34638692, 2021).
autosomal recessive disease (3 papers, 2018 to 2023). Autosomal recessive form of disease. "Other more representative genes were CEP290, USH2A, and CRB1 that caused autosomal recessive diseases and RPGR and CHM that caused X-linked IRD; each one accounted for about 5% of the conclusive results." (PMID 30374144, 2018).
neurodegenerative disease (1 paper, 2017). A disorder of the central nervous system characterized by gradual and progressive loss of neural tissue and neurologic function. "The patient-derived USH2A mutant photoreceptors had upregulation of GRP78 and GRP94, suggesting that mutations in USH2A can cause endoplasmic reticulum stress, which occurs frequently in neurodegenerative diseases." (PMID 28596937, 2017).
USH2A also shares sentences with these, for which no sentence is quoted: Hearing impairment (18 papers); Blindness (8); autosomal recessive retinitis pigmentosa (6); Usher syndrome type 1 (6); Bardet-Biedl syndrome (4); lung carcinoma (4); choroideremia (3); autosomal recessive hearing loss (2); colon adenocarcinoma (2); cone dystrophy (2); Duchenne muscular dystrophy (2); Leber congenital amaurosis 10 (2); lung squamous cell carcinoma (2); nonsyndromic deafness (2); recessive retinitis pigmentosa (2); Alström syndrome (1); artery disease (1); Atrophy (1); Bietti crystalline dystrophy (1); cardiomyopathy (1); cataract (1); CHARGE syndrome (1); Chediak-Higashi syndrome (1); congenital retinoschisis (1); corneal diseases (1); cystic fibrosis (1); developmental delay (1); epilepsy (1); equinovarus (1); familial atrial fibrillation 3 (1).
A further 38 diseases each share a sentence with USH2A in 1 paper.